NEDD4L (NEDD4 like E3 ubiquitin protein ligase)
Diseases named in the same sentence as NEDD4L in open-access papers (continued):
Sharing a sentence is not in itself a finding about the gene and the disease.
myocardial infarction (8 papers, 2009 to 2025). Gross necrosis of the myocardium, as a result of interruption of the blood supply to the area, as in coronary thrombosis. "Y-box-binding protein 1 (Ybx1) is an essential transcriptional protein in myocardial proliferation after myocardial infarction, which acts as a substrate for Nedd4L and can bind to Nedd4L for degradation." (PMID 35429991, 2022). "In addition, to improve these limitations, we will explore the role of NEDD4L in regulating hind‐limb and myocardial infarction using endothelial cell‐specific knock‐out or knock‐in mice in our future study." (PMID 38526036, 2024). "Pharmacological or genetic NEDD4L modulation may be a promising therapeutic strategy that can be considered in the treatment of ischemic diseases, such as myocardial infarction, exacerbation of diabetic retinopathy, and limb ischemia, due to the stimulation of angiogenesis in the ischemic tissues." (PMID 40136477, 2025). "In addition, pharmacological or genetic promotion of NEDD4L may represent a promising therapeutic strategy for treating ischemic diseases, such as myocardial infarction, which exacerbates diabetic retinopathy and critical limb ischemia, by promoting an angiogenic role in the ischemic tissues." (PMID 40136477, 2025). "In addition, pharmacological or genetic promotion of NEDD4L may represent a promising therapeutic strategy for treating ischemic diseases, such as myocardial infarction, exacerbates diabetic retinopathy and critical limb ischemia, by promoting angiogenic role in the ischemic tissues." (PMID 38526036, 2024). "In addition, defection of the NEDD4L C2 isoform changes cardiac conduction in the resting state as well as pro-arrhythmic alterations upon acute myocardial infarction (MI)." (PMID 33110392, 2020). "The third limitation is that we have not selected a specific activator of NEDD4L for treating ischemic disease, such as myocardial infarction, diabetes‐related limb ischemia." (PMID 38526036, 2024).
non-small cell lung carcinoma (8 papers, 2015 to 2022). A group of at least three distinct histological types of lung cancer, including non-small cell squamous cell carcinoma, adenocarcinoma, and large cell carcinoma. "It is reported that NEDD4L expression level is significantly down-regulated in non-small cell lung cancer." (PMID 34539897, 2021).
diabetes (7 papers, 2024 to 2026). "This insight offers a potential therapeutic strategy targeting NEDD4L and CaMKKβ to preserve renal tubular function in the context of diabetes." (PMID 38755664, 2024). "Hence, in this study we analysed NEDD4L expression in kidney biopsies from patients with Type 2 diabetes mellitus (T2DM) and DN, as well as the release of urinary EVs from patients with DN and control subjects without diabetes." (PMID 41809111, 2026). "Furthermore, a study utilising unbiased single-nucleus RNA sequencing of human kidneys from patients with diabetes showed a significant down-regulation of NEDD4L in DKD, correlating with aberrant electrolyte transport." (PMID 40617804, 2025). "In addition, this ligase also acts in some human diseases, such as diabetic kidney disease (in diabetic nephropathy, NEDD4L increased high-glucose (HG)-induced podocyte inflammatory injury), diabetes, and atherosclerosis." (PMID 40136477, 2025). "The finding that NEDD4L reduction and subsequent ENaC elevation in diabetes reduces aldosterone levels and therefore BGL provides mechanistic insight into how reduction of aldosterone may improve glucose homeostasis." (PMID 40617804, 2025). "Although it may offer a new strategy to counteract atherosclerosis via medicinal plants and bioactive compounds targeting NEDD4L under diabetic conditions, further studies must be conducted to evaluate whether SHENQI intervenes directly in diabetes associated with NEDD4L." (PMID 40136477, 2025). "RAB11FIP3‐FL can promote the ubiquitination and degradation of HIF‐1α through the combination of NEDD4L and HIF‐1 α, thus inhibiting the proliferation, migration and tubular formation of vascular endothelial cells and suppressing the healing of diabetes wounds." (PMID 40758539, 2025).
diabetic nephropathy (7 papers, 2013 to 2026). "Three recent population-based studies found human NEDD4L variants associated with type 2 diabetes, obesity and diabetic nephropathy." (PMID 24147136, 2013). "It will be interesting to investigate other possible metabolic roles of NEDD4L isoforms in liver in vivo in Nedd4l knockout mice to help determine why mutations in human NEDD4L loci are associated with risk for type 2 diabetes, obesity and diabetic nephropathy." (PMID 24147136, 2013). "NEDD4L has been reported to bind to IKKα/β and IκBα, aggravating the inflammatory damage of diabetic nephropathy." (PMID 40399270, 2025). "In conclusion, these findings highlight the significance of aberrant NEDD4L expression in disrupting mitochondrial homeostasis by downregulating CaMKKβ in diabetic kidney disease." (PMID 38755664, 2024). "For instance, miR-98 by directly targeting NEDD4L played a key role in alleviating renal fibrosis in diabetic nephropathy." (PMID 34809620, 2021). "In addition, decreased expression of NEDD4L (human Nedd4-2) has been correlated with early stage human diabetic nephropathy." (PMID 31802037, 2020). "NEDD4L variants in patients with CKD-like pathologies have not yet been characterized, however decreased expression of NEDD4L has recently been observed in early diabetic nephropathy." (PMID 31802037, 2020).
heart failure (7 papers, 2019 to 2024). Inability of the heart to pump blood at an adequate rate to meet tissue metabolic requirements. "NEDD4L accelerates the degradation of the cardiac sodium channel Nav1.5 through ubiquitination in the heart, which is associated with heart failure." (PMID 36291692, 2022). "PTVs in membrane receptor regulator NEDD4L were associated with DCM (OR = 10.4, Padj = 0.01) P and with quantitative traits in UKB (PTV: LVEDV = +29.7, Padj = 0.02; LVESV = +19.8, Padj = 0.005), with replication in GeL (heart failure OR = 13.0, P = 0.01)." (PMID 39572783, 2024). "Elevated NEDD4L expression and decreased NaV1.5 protein levels have been reported in volume-overload heart failure rat models, suggesting that NEDD4L-mediation of ubiquitination of NaV1.5 may contribute to the pathophysiology of heart failure." (PMID 38309503, 2024). "Results from this landmark study thus suggest that targeting the Nedd4L/TrkA/cAMP pathway may be a potential novel promising option for the prevention and treatment of heart failure." (PMID 35429991, 2022). "In addition, Nedd4L and its colocalization with sodium channels are also increased in case of heart failure." (PMID 35429991, 2022).
hepatocellular carcinoma (7 papers, 2021 to 2024). A malignant tumor that arises from hepatocytes. "Furthermore, in hepatocellular carcinoma, downregulation of NEDD4L promotes tumour growth and inhibits MAPK/Erk1/2 signal pathway." (PMID 38526036, 2024). "Besides, NEDD4L protein expression was downregulated in several different hepatocellular carcinoma cell lines compared to that in normal liver cell lines." (PMID 38027016, 2023). "A recent study pointed out that downregulation of NEDD4L promoted hepatocellular carcinoma growth." (PMID 34305532, 2021). "Additionally, NEDD4L induces apoptosis in hepatoma and leukemia cells." (PMID 38027016, 2023). "In hepatocellular carcinoma (HCC), NEDD4L inhibits cell proliferation via the MAPK/ERK pathway." (PMID 38027016, 2023). "However, the protein level of PSMD2 and PSMC3 didn’t change in other NEDD4L-KD turmor cells such as hepatocellular carcinoma (HCC) cells." (PMID 35236820, 2022).
bladder cancer (6 papers, 2022 to 2024). "Two E3 ligases were identified, E3 ubiquitin-protein ligase (MIB2) and E3 ubiquitin protein ligase NEDD4 like (NEDD4L), that were significantly downregulated in the separated sEVs of patients with a first diagnosis of bladder cancer." (PMID 37371512, 2023). "In bladder cancer, long non-coding RNA H19 from the exosomes of M2 tumor-associated macrophages interfers K48-linked polyubiquitination of ULK1 mediated by NEDD4L, stabilizing ULK1 expression and promoting bladder cancer cell autophagy." (PMID 38027016, 2023). "Simultaneously, in light of NEDD4L could reduce cisplatin resistance and induce apoptosis in bladder cancer, exploring the role of NEDD4L in the drug resistance through ferroptosis will open novel avenue for human cancer treatment strategies." (PMID 39557844, 2024). "NEDD4L inhibits bladder cancer progression by inactivating the p62/Keap1/Nrf2 pathway." (PMID 38526036, 2024). "Additionally, NEDD4L inactivates the p62/Keap1/Nrf2 pathway, inhibiting bladder cancer cell migration and invasion." (PMID 38027016, 2023). "In addition, NEDD4L inhibits cisplatin resistance in bladder cancer cells by inactivating the p62/Keap1/Nrf2 pathway." (PMID 38027016, 2023). "NEDD4L also inactivates the p62/Keap1/Nrf2 pathway to promote bladder cancer cell apoptosis." (PMID 38027016, 2023). "lncRNA H19-silenced exosomes from TAMs led to a significant increase in the interaction between NEDD4L and ULK1, whereas lncRNA H19 overexpression suppressed the interactions between NEDD4L and ULK1 in bladder cancer cells." (PMID 37568787, 2023). "Long non-coding RNA H19 from the exosomes of M2 tumor-associated macrophages inhibits the interaction between ULK1 and its specific E3 ubiquitin ligase NEDD4L, stabilizing ULK1 expression and promoting autophagy in bladder cancer cells." (PMID 38027016, 2023).
colon cancer (6 papers, 2019 to 2025). "Using tissue microarray–based IHC of colon sections from patients with CRC, we found that protein expression of NEDD4L was significantly inhibited in IECs of colonic tumor tissues compared with normal tissues." (PMID 39688910, 2024). "To clarify the role of Nedd4 and Nedd4l in intestinal tumorigenesis, we further crossed the mutant mice to Apcmin animals, a mouse model of colon cancer, to obtain Apcmin Nedd4 cKO, Apcmin Nedd4l cKO, and the compound Apcmin DKO mice." (PMID 31867777, 2020). "A previous study reported that NEDD4L is a negative regulator of the Wnt/β-catenin pathway in colon cancer." (PMID 31805126, 2019). "FOXP1 and NEDD4L are plausible tumor suppressor genes in colon cancer." (PMID 40753397, 2025). "In colon cancer cells, (P)RR dramatically inhibits the NEDD4L-mediated Wnt3 protein ubiquitination." (PMID 36597142, 2023). "We then used the Ualcan dataset to select four candidate E3 ligases (TRIM25, HECTD3, NEDD4L, WWP2) whose mRNA levels were lower in colon cancer tissue samples compared to normal colon tissues." (PMID 38803048, 2024). "Colitis is a risk factor for colon cancer and AOM/DSS model mice have more severe inflammation, which would drive more serious cancer regardless of any cell-intrinsic effect, suggesting that blocking IL-17R signaling may have no influence on CAC mediated by Nedd4l IEC deficiency." (PMID 39688910, 2024).
gallbladder cancer (6 papers, 2013 to 2024). "Using siRNA, silencing of NEDD4L led to decreased Matrigel and collagen invasion of gallbladder cancer cells, and its role in invasion is possibly due to its association with MMPs." (PMID 25079072, 2014). "NEDD4L is an E3 ubiquitin-ligase shown to have increased expression with gallbladder cancer progression." (PMID 25079072, 2014). "Moreover, mRNA and protein levels of NEDD4L are much higher in the cytoplasm of invasive gallbladder cancer cells than in normal or dysplastic epithelial cells." (PMID 38027016, 2023). "In addition, NEDD4L overexpression may lead to gallbladder cancer invasion by decreasing the transcription of MMP1 and MMP13." (PMID 38027016, 2023). "Notably, the downregulation of NEDD4L cannot affect the growth of gallbladder cancer cells." (PMID 38027016, 2023). "Moreover, the upregulation of NEDD4L enhances the transcription of MMP1 and MMP13, leading to aggressive gallbladder cancer." (PMID 38027016, 2023). "Interestingly, downregulation of NEDD4L did not affect cell growth in gallbladder cancer." (PMID 34869021, 2021). "Unlike with most cancer types, NEDD4L might exert a tumor-promoting effect on gallbladder cancer." (PMID 34869021, 2021).
periventricular nodular heterotopia (6 papers, 2018 to 2024). Periventricular nodular heterotopia (PNH) is a brain malformation, due to abnormal neuronal migration, in which a subset of neurons fails to migrate into the developing cerebral cortex and remains as nodules that line the ventricular surface. "Mutations of NEDD4L lead to Akt–mTOR pathway deregulation and cause periventricular nodular heterotopia." (PMID 38526036, 2024). "Missense variants in NEDD4L have been reported in nine patients with periventricular nodular heterotopia (PNH), polymicrogyria, cleft palate, and syndactyly." (PMID 32117442, 2020). "Heterozygous mutations in the NEDD4L gene have recently been identified to cause a novel syndromic form of periventricular nodular heterotopia in humans (PVNH7; OMIM #617201)." (PMID 30393983, 2018). "With the identification of heterozygous mutations in the HECT domain of NEDD4L, an additional genetic form of periventricular nodular heterotopia has been identified." (PMID 30393983, 2018). "Here, we describe a girl with a novel heterozygous NEDD4L missense variant, p.Tyr679His, and characteristic clinical findings, including bilateral periventricular nodular heterotopia, cleft palate and mild toe syndactyly." (PMID 30393983, 2018). "Interestingly, P1 also harboured a second de novo deletion involving NEDD4L, a gene linked to periventricular nodular heterotopia." (PMID 40225164, 2023). "Periventricular nodular heterotopia-7 (PVNH7) is a neurodevelopmental disorder associated with improper neuronal migration during neurogenesis in cortex development caused by pathogenic variants in the NEDD4L gene." (PMID 34087865, 2021). "Mutations in the HECT domain of NEDD4L have recently been identified in a cohort of eight patients with a syndromic form of bilateral periventricular nodular heterotopia (PVNH) in association with neurodevelopmental delay, cleft palate, and toe syndactyly (PVNH7)." (PMID 30393983, 2018).
cardiac hypertrophy (5 papers, 2016 to 2022). "Cardiac hypertrophy and significantly decreased cardiac function were detected in Nedd4L knockout mice fed with chronic high-salt diet." (PMID 35429991, 2022). "Therefore, wogonin targets Nedd4l to induce the degradation of Pik3ca, which reverses the over-activation of the PI3K/Akt pathway and consequently relieves the isoprenaline-induced myocardial hypertrophy." (PMID 30150938, 2018).
clear cell renal cell carcinoma (5 papers, 2021 to 2025). "In renal clear cell carcinoma, NEDD4L overexpression significantly reduced malignant manifestations such as cell proliferation and migration." (PMID 39717922, 2025). "As previously documented, bioinformatics analysis revealed NEDD4L is downregulated in clear cell renal cell carcinoma (ccRCC)." (PMID 39596003, 2024). "NEDD4L was found to be downregulated and correlated with biosynthesis and metabolism in clear-cell renal cell cancer (ccRCC) by integrated bioinformatics analysis." (PMID 34869021, 2021). "Paired analysis showed that the level of NEDD4L mRNA in renal clear cell carcinoma tissue was significantly reduced (p <0.0001)." (PMID 34539897, 2021). "Furthermore, the low expression of NEDD4L was verified in our clear cell renal cell carcinoma (ccRCC) clinical tissues." (PMID 34539897, 2021). "Low expression of NEDD4L gene predicts poor overall survival and disease-specific survival (DSS) in renal clear cell carcinoma (KIRC) and renal chromophobe cell carcinoma (KIRP)." (PMID 34539897, 2021). "It was reported that the expression of NEDD4L was positively related to overall survival and disease-specific survival (DSS) in clear cell renal cell carcinoma (ccRCC) and chromophobe cell renal carcinoma (CCRC)." (PMID 34869021, 2021).
cystic fibrosis (5 papers, 2014 to 2021). Autosomal recessive disorder caused by pathogenic variants in the CFTR gene (cystic fibrosis transmembrane conductance regulator), which encodes a chloride and bicarbonate channel expressed in epithelial cells, and follow the diagnosis criteria. "NEDD4L is expressed in bronchial epithelial cells and a conditional knockout of this gene in mice leads to a cystic fibrosis-like phenotype including inflammation and mucus overproduction, also features of asthma, suggesting that this gene plays an important role in the lung." (PMID 25116239, 2014).